LEP (leptin)
Diseases named in the same sentence as LEP in open-access papers (continued):
Sharing a sentence is not in itself a finding about the gene and the disease.
Obesity (continued). "Given these connections between mitochondrial morphology, adipokines, obesity, and cancer, it will be important to assess the effects of SH‐BC‐893 on mitochondria in tumors and its effectiveness in tumor models that are sensitive to a HFD and/or leptin and insulin levels." (PMID 34231322, 2021). "It is conceivable that metabolic abnormalities in LEP/LEPR heterozygosity may be secondary to overweight or obesity, irrespective of the genetic status, is conceivable." (PMID 34448070, 2021). "Moreover, the studies have shown that a decreased concentration of adiponectin and interleukin 10 and an increased concentration of leptin, resistin, interleukin 6, and MCP-1 could be a potential marker of obesity and its accompanying disorders." (PMID 34769133, 2021). "The origin of obesity in cancer survivors is not fully explained, but likely includes physical inactivity, damage to the hypothalamus and endocrine organs, and resistance to insulin and leptin, among others." (PMID 32153654, 2020). "Since leptin functions as a physiological and anorexic counteragent to ghrelin in the hypothalamus, blocking intraneuronal AG/GHS-R1α-signaling, some studies have suggested that the elevated plasma pools of leptin during obesity weaken the sensitivity toward AG." (PMID 33381011, 2020). "Overall, the present results show that high leptin levels may be found in climacteric women in the absence of an elevated BMI or other signs of obesity." (PMID 32555994, 2020). "However, in obesity, food intake is not reduced despite a rise in leptin level, a phenomenon referred to as leptin resistance." (PMID 32668680, 2020). "The connection between NPY and leptin has been long recognized: on one hand, NPY is overexpressed in the hypothalamus of ob/ob mice, and its repetitive administration into the CNS was shown to suppress the SNS activity of BAT, decreasing energy expenditure and inducing obesity." (PMID 32069871, 2020). "Further studies are necessary to determine the link between glucose metabolism, peripheral hormones (such as GLP-1, leptin and ghrelin), BDNF and hippocampal 5-HTT signaling and its biological relevance with regard to preventive and therapeutic consequences in individuals with obesity." (PMID 33288788, 2020). "Leptin has been shown to be increased in obese patients and to mediate the development of obesity hypertension in studies using non-pregnant rodents; this occurs via downstream signaling of the melanocortin-4 receptor (MC4R) in the brain that promotes sympathetic drive and hypertension." (PMID 32817646, 2020). "This may be because obesity increases the mechanical load of articular cartilage, leading to its degradation, and fatty tissue secretes metabolic factors (such as IL-1, TNF-A, adiponectin, and leptin), leading to an increased prevalence of OA in obese people." (PMID 33409277, 2020). "The implication that presence of LepR on cells of degenerated human IVD is directly related to negative effects of leptin—whose serum levels increase exponentially with an increasing volume of adipose tissue—likely oversimplifies the complex relationship between obesity, leptin pathway, and LDD." (PMID 33396484, 2020). "Third, this study failed to include some new obesity biomarkers (such as leptin and adiponectin) that may further improve the prediction of metabolic syndrome." (PMID 32202504, 2020). "Therefore, leptin treatment in individuals with obesity who exhibit adequate or even elevated leptin levels has not been as beneficial as once hoped." (PMID 33292104, 2020). "In addition, previous studies found that exogenous leptin treatment in mice induced higher levels of SOCS3 in the hypothalamus, and mice with obesity induced by a high-fat diet do not respond to exogenous leptin treatment due to leptin resistance." (PMID 32846917, 2020). "However, the range of obesity does not influence the values of leptin expression in PCa tissue, unlike the leptin values in blood." (PMID 32573960, 2020).
Obesity (continued). "Leptin may upregulate the production of inflammatory cytokines such as CRP, TNF-α, IL-6, and IL-12 and be involved in low-grade inflammation, which plays a central role in the pathophysiology of obesity, depression, metabolic and cardiovascular disease." (PMID 33036196, 2020). "While it is well-known that circulating leptin levels in the blood are related to body fat composition, our study confirms that the distribution of obesity, rather than overall obesity, is critical for the development of insulin resistance and incident type 2 diabetes mellitus." (PMID 32131811, 2020). "Interestingly, a research on 122 AMI patients admitted in ICU showed no notable change in serum leptin level but was elevated in patients with obesity, high BMI and waist circumference." (PMID 33489600, 2020). "In obesity, omentin circulating and expression levels in VAT are decreased, correlating positively with plasma adiponectin and high-density lipoprotein (HDL) levels and negatively with the waist circumference, BMI, leptin and fasting insulin levels, and it is considered a marker of leanness." (PMID 33081064, 2020). "However, CLA supplementation failed to reduce the concentration of this hormone as well as to restore the hepatic leptin sensitivity in these animals, indicating that the anti-obesity effect of CLA is independent of the leptin system." (PMID 32033223, 2020). "In addition, intraperitoneal injection of leptin in wild type mice with no obesity increased mitotic counts during liver regeneration." (PMID 32578019, 2020). "Oral administration of scopolin in an OVX-induced obesity mouse model revealed that scopolin prevented OVX-induced weight gain, an increase in body fat percentage, hepatic steatosis, and an increase in epididymal fat by downregulating serum leptin and insulin levels." (PMID 33218042, 2020). "They demonstrated that HT could prevent obesity, hyperglycemia, and insulin resistance, after 17 weeks of supplementation in db/db mice, a model of metabolic syndrome (MetS) with obesity and type 2 diabetes induced by the nonfunctional leptin pathway." (PMID 32825589, 2020). "However, CME ameliorated HFD increased food intake, body weight gain, hyperglycemia and dyslipidemia through normalization of HFD reduced leptin, adiponectin and UCP1 synthesis and production as well as its antioxidant activity suggesting that CME is a potent anti-obesity agent." (PMID 32197395, 2020). "Mice lacking PTP1B are hypersensitive to leptin resistance, obesity, and insulin level." (PMID 33273564, 2020). "The adipokines, including adiponectin and leptin, have been demonstrated to signal through the hypothalamus to control whole-body metabolism, including modulation of sympathetic output to adipose tissue and directly modulate macrophage status in WAT, and thermogenesis in BAT during obesity." (PMID 33353562, 2020). "It is thought that diet-induced obesity renders AgRP neurons resistant to the effects of leptin, based in part on the fact that exogenous leptin fails to reduce food intake or induce pSTAT3 in obese animals and does not inhibit AgRP neurons in ex vivo preparations from obese animals." (PMID 32720646, 2020). "Obesity determines an increase in free leptin levels as a result of the increase in leptin and decrease of its soluble receptor, that is not reproduced in the spinal fluid, leading to “leptin resistance”." (PMID 33137934, 2020). "In these regions, leptin signaling is mediated by the JAK2/Stat3 pathway, in which several negative regulators of JAK2, including SOCS3 and PTP1B, have been reported to promote obesity, supporting the notion that JAK2 inhibitory molecules increase risk for leptin resistance and obesity." (PMID 32630697, 2020).
Obesity (continued). "The main findings of this study indicate that obesity promotes elevation of adiposity and hyperleptinemia, and RT was able to promote strength increase, reducing leptin levels and epididymal and visceral fat pads without changes in total adiposity and other comorbidities." (PMID 32714085, 2020). "Third, we could not analyze blood parameters related to obesity and metabolic dysfunction such as adiponectin, leptin, and insulin levels because of lack of data." (PMID 32365676, 2020). "However, according to our results, this pathway is partially activated in this model of obesity, since the Akt inhibition did not change the endothelium-mediated dilation with either acetylcholine or leptin to the same level as observed in C animals." (PMID 30949067, 2019). "However, studies in ob/ob mice have demonstrated that the absence of leptin leads to obesity, hyperlipidaemia and insulin resistance, while leptin administration reverses these metabolic perturbations." (PMID 30863366, 2019). "In particular, we address the question as to whether circulating levels of pro-inflammatory markers, such as leptin and IL-6, or markers of cerebral plasticity, such as BDND and S100B, are related to the temporal sensitivity in obesity, through a cross-sectional study." (PMID 31664059, 2019). "In other studies that utilized rats with diet-induced obesity, CB1 receptor expression in the kidney is notably upregulated, and treatment with a CB1 receptor antagonist reduced weight, systolic blood pressure, plasma leptin, albuminuria, and plasma creatinine levels." (PMID 31346545, 2019). "Interestingly, we observed similar patterns of expression of genes encoding secreted factors in aged and obese adipose tissues, suggesting that PMATs act as a common accelerator of obesity- and aging-related muscle atrophy via those secreted proteins, among them, PAI-1, Leptin, and Fgf21." (PMID 31442231, 2019). "Interestingly, data support a U-shaped mechanism whereby low and high concentrations of leptin present in malnutrition and obesity, respectively, negatively impact HPC synaptic plasticity and cognitive function." (PMID 31057368, 2019). "Conversely, TNF-α was positively related, and IL-6, leptin, insulin, total n-6, n-3 and n-6/n-3 PUFAs in whey breastmilk were negatively correlated to several infant growth measures in offspring of women without overweight or obesity." (PMID 31141526, 2019). "However, it has been shown that in obese people, there is a high level of Leptin which correlates positively with adipose tissue and does not have any effect of reducing nutrition and thus preventing obesity." (PMID 31871931, 2019). "However, relationship between the catecholamine level and plasma leptin in obesity has not yet been investigated." (PMID 31682617, 2019). "The aim of this study was to test the hypothesis that unsaturated high-fat diet-induced obesity does not generate endothelial dysfunction via increasing the vascular leptin/Akt/eNOS signaling." (PMID 30949067, 2019). "Furthermore, negative correlations were observed in normal-weight mothers between the expression of miRNAs in milk and the concentration of leptin or adiponectin, but were absent in overweight/obesity." (PMID 31661820, 2019). "If one or more such hormones existed, understanding their role in physiology and disease might offer approaches to obesity treatment that leptin has so far not provided." (PMID 30357355, 2019). "Thus, despite being a single factor amongst many, which is studied here in isolation, it is not impossible that leptin contributes significantly to the dysregulated/activated adipose tissue autophagy and to this tissue’s dysfunction in obesity." (PMID 30676227, 2019).
Obesity (continued). "This can be explained by the higher levels of IGF-1 in obesity, which is the real hormone responsible for growth, just as early puberty in these cases can be explained by the increase in IGF-1 itself and the high levels of leptin produced by the excessive fat tissue." (PMID 31379735, 2019). "Yet, whether adipocytes exhibit leptin resistance is not unclear: several papers concluded that obesity induces leptin resistance in whole AT,46,47 characterized by decreased pSTAT3 levels and elevated SOCS-3 expression." (PMID 30676227, 2019). "We cannot exclude that in the ob/ob model with a C57BL/6 background, the absence of leptin production could be a limitation in the exploration of sex-dependent lipid profile in obesity and its translation to humans." (PMID 30808418, 2019). "Importantly, the leptin in cerebrospinal fluid is only modestly elevated in obesity independent of hyperleptinemia." (PMID 31408957, 2019). "In conclusion, the high-unsaturated fat (49.2 energy from fat) diet-induced obesity improved the vascular reactivity to leptin and does not generate endothelial dysfunction, possibly by the increase in the vascular sensitivity to leptin and increasing NO bioavailability." (PMID 30949067, 2019). "To further investigate whether the body composition analyzer is sensitive enough to detect liver steatosis in smaller animals, we studied genetically obese mice that develop severe obesity due to the lack of leptin action." (PMID 31756971, 2019). "Therefore, glucose homeostasis in our experimental animals was predominantly affected by the former obesity rather than by the absence of leptin signaling during development." (PMID 30694175, 2019). "Application of the peroxisome proliferator activated receptor gamma (PPARγ) Ligand rosiglitazone further increased the leptin concentrations in BAL, suggesting that treatment of obesity-related type II diabetes may result in higher leptin levels in the lung system." (PMID 30832310, 2019). "Moreover, one study in adolescent males with obesity showed a negative correlation between INSL3 and leptin levels (r = −0.468, p = 0.001), further illustrating leptin’s association with reduced Leydig function and hypogonadism." (PMID 31052376, 2019). "Interestingly, basal norepinephrine was well-correlated with the plasma leptin, but not plasma insulin in obesity." (PMID 31682617, 2019). "Increased leptin level predicts metabolic syndrome development independent of obesity." (PMID 31341853, 2019). "Whether this evolutionary explanation is true or not, identification of mechanisms by which leptin physiologic action becomes saturated at relatively low leptin levels might suggest therapeutic approaches to enhancing leptin action to treat obesity." (PMID 30357355, 2019). "Studies in healthy humans and patients with lipodystrophy examining hepatic VLDL secretion will also provide key evidence for a potential utility of recombinant leptin as a novel drug for treating obesity-related NAFLD, for which no clinically effective therapy is yet available." (PMID 31222048, 2019). "Remarkably, our results showed an ability of RSV at 200 mg/kg to normalize tissue fat content and leptin expression and secretion as well as to enhance peripheral leptin sensitivity, highlighting the overall beneficial effect of RSV in the modulation of diet-induced obesity at this dose." (PMID 30441779, 2018). "Several biological mechanisms, ranging from systemic inflammation, leptin resistance, metabolic syndrome disturbances, dysregulated hypothalamus–pituitary–adrenal axis (HPA-axis) have been proposed to be linking mechanisms between depression and obesity as these all occur in both conditions." (PMID 29644388, 2018). "However, the presence and properties of leptin-reactive IgG have not been studied in obesity and diabetes." (PMID 29795184, 2018).
Obesity (continued). "The LHZR, a simple obesity control carrying genotype of the LZR, displayed hypercapnia, respiratory acidosis, relatively normal serum leptin, basal hypoventilation and moderate response to hypoxia, probably representing a model of simple obesity rather than leptin resistance." (PMID 29636698, 2018). "Thus, while physical exercise exerts a profound action in the control of obesity in some obesity models, it is unclear why physical exercise is ineffective in obese animals lacking leptin or leptin receptors." (PMID 29896090, 2018). "The strongest negative correlations were observed with obesity measures and leptin." (PMID 29691431, 2018). "Although effective leptin therapy for treating obesity and diabetes is not established, mainly due to leptin resistance in obese patients, there are several clinical trials for combined therapies to improve the treatment of obesity-related conditions and lipodystrophy." (PMID 29467755, 2018). "Moreover, the obesity-stratified logistic regression analysis showed that lower adiponectin and higher leptin predict PTS suggesting that their harmful effect is independent of obesity." (PMID 29720688, 2018). "However, too much leptin can lead to leptin resistance wherein the anti-obesity properties are no longer triggered." (PMID 30127766, 2018). "So our results also confirmed the negative effects of leptin/lepR related obesity on reproduction." (PMID 29728128, 2018). "In addition, in the absence of NPY, the obesity and sterility normally exhibited by leptin-deficient ob/ob mice were attenuated, indicating that NPY functions as a central effector of leptin deficiency." (PMID 29976877, 2018). "In obesity, we have increased adiposity with greater adipocyte size and number, leading to a higher leptin concentration, but without reduced food intake (leptin resistance), which is an example of the consequences of altering the neuro-endocrine system controlling energy homeostasis." (PMID 30463389, 2018). "Remarkably, leptin and insulin both require the NSAPP oxide transport chain, suggesting that a defect in this pathway could explain simultaneous resistance to the appetite-suppressing effects of both hormones in obesity." (PMID 29632515, 2018). "Although exercise reduces leptin levels in proportion to the triglyceride content of white adipose tissue in obese individuals, evidence in humans to support the role of exercise in reducing obesity-related leptin resistance is lacking." (PMID 29867590, 2018). "However, in obesity and diabetes, elevated circulatory levels of leptin do not drive the same appetite feedback responses." (PMID 30567565, 2018). "Taking advantage of this, our purpose was to determine, in DIO mice, the isolated effect of exercise (without body weight modification) on insulin and leptin action on hypothalamus, on peripheral insulin sensitivity, and glucose homeostasis, all of which are negatively affected by obesity." (PMID 29371411, 2018). "While alterations in insulin and leptin levels have been found in mothers fed hypercaloric diets during pregnancy and lactation, it is important to point out that in our murine model, maternal hypercaloric diet intake does not develop obesity in mothers." (PMID 29991958, 2018). "Thus, LepRbHtr2c neurons play a minimal role in the control of energy balance by leptin, and deletion of LepRb from approximately half of hypothalamic LepRb neurons does not necessitate obesity if the important cells are not impacted." (PMID 29914853, 2018). "In addition boys with obesity had higher concentrations of insulin and leptin and lower concentrations of HDL-cholesterol compared to normal weight boys." (PMID 30266914, 2018). "Given links of obesity to PTS2,10,14,15 and experimental data on the impact of adipokines on prothrombotic mechanisms in various models, we conducted a prospective cohort study to assess a predictive value of resistin, adiponectin and leptin in the PTS development." (PMID 29720688, 2018).